LIPC (lipase C, hepatic type)
Description:
Catalyzes the hydrolysis of triglycerides and phospholipids present in circulating plasma lipoproteins, including chylomicrons, intermediate density lipoproteins (IDL), low density lipoproteins (LDL) of large size and high density lipoproteins (HDL), releasing free fatty acids (FFA) and smaller lipoprotein particles. Also exhibits lysophospholipase activity (By similarity). Can hydrolyze both neutral lipid and phospholipid substrates but shows a greater binding affinity for neutral lipid substrates than phospholipid substrates (By similarity). In native LDL, preferentially hydrolyzes the phosphatidylcholine species containing polyunsaturated fatty acids at sn-2 position.
Synonyms: HL; HTGL; HDLCQ12
Tractability: Small molecule: a high-quality ligand is known; it belongs to a druggable protein family. Antibody: UniProt places it where antibodies can reach, with high confidence; its Gene Ontology location is reachable by antibodies, with high confidence; UniProt predicts a signal peptide or a membrane-spanning region. PROTAC: its protein half-life has been measured; a small molecule that binds it is known.
Target class: Enzyme; Hydrolase
Gene: Protein-coding gene on chromosome 15 (58,410,380 to 58,570,449, forward strand). Ensembl gene ENSG00000166035.
Subcellular location: Secreted
Pathways (Reactome):
Transport of small molecules: Assembly of active LPL and LIPC lipase complexes; Chylomicron clearance
Gene Ontology:
Molecular function: phospholipase A1 activity; protein binding; triacylglycerol lipase activity; apolipoprotein binding; lipoprotein lipase activity; low-density lipoprotein particle binding; phosphatidylcholine lysophospholipase activity; phospholipase activity; carboxylic ester hydrolase activity; diacylglycerol lipase activity; lipase activity
Biological process: cholesterol homeostasis; fatty acid biosynthetic process; high-density lipoprotein particle remodeling; low-density lipoprotein particle remodeling; triglyceride catabolic process; triglyceride homeostasis; very-low-density lipoprotein particle remodeling; chylomicron remnant clearance; intermediate-density lipoprotein particle remodeling; phosphatidylcholine catabolic process; reverse cholesterol transport; lipid metabolic process
Cellular component: extracellular region; endoplasmic reticulum lumen
Genetic constraint (gnomAD): Loss-of-function variants: 35 observed, 42.12 expected, observed/expected ratio (o/e) 0.83, 90% interval 0.63 to 1.1. The upper end of that interval is the gene's LOEUF score, 1.1, which puts it in group 4 of 6, group 1 being the genes least tolerant of losing a copy. Missense variants: 591 observed, 564.67 expected, observed/expected ratio (o/e) 1.05, 90% interval 0.98 to 1.12. Synonymous variants: 245 observed, 233.5 expected, observed/expected ratio (o/e) 1.05, 90% interval 0.94 to 1.17.
Homologues: Orthologues: chimpanzee LIPC (99% identical), macaque LIPC (95% identical), rabbit LIPC (80% identical), pig LIPC (79% identical), dog LIPC (78% identical), mouse Lipc (75% identical), rat Lipc (74% identical), guinea pig LIPC (65% identical), tropical clawed frog lipc (58% identical), zebrafish lipca (51% identical), zebrafish lipcb (25% identical), Drosophila melanogaster CG6296 (23% identical), and 14 more. Paralogues in human: LPL (42% identical), LIPG (40% identical), PNLIPRP1 (28% identical), LIPH (28% identical), PNLIP (28% identical), PNLIPRP3 (27% identical), PNLIPRP2 (27% identical), LIPI (27% identical), PLA1A (25% identical).
Diseases named in the same sentence as LIPC in open-access papers:
LIPC is named in the same sentence as 84 diseases in open-access papers, as found by Europe PMC text mining. Sharing a sentence is not in itself a finding about the gene and the disease. The quoted sentences say what the papers report.
dyslipidemia (35 papers, 2011 to 2026). "The condition is classified as autosomal recessive, since dyslipidemia is inconsistently observed in heterozygous patients with only one LIPC variant." (PMID 39518997, 2024). "We studied the PAV and PTV burden in 19 genes causing monogenic dyslipidemias and overlapping previous lipid GWAS loci, including the LIPC gene (p<0.05/19 = 0.0026 considered significant after correction for multiple testing)." (PMID 36419110, 2022). "The pleiotropic associations further support a complex interaction between LIPC SNPs and the risk of metabolic syndromes, diabetes mellitus and future atherosclerotic cardiovascular disease." (PMID 30410583, 2018). "Furthermore, it was proposed that a second factor would be necessary for expression of dyslipidemia in simple heterozygotes for LIPC variants." (PMID 39518997, 2024). "Variants of the LIPC gene are well known to be associated with dyslipidemia." (PMID 31910446, 2020). "Interestingly, four of the top five significant genes (GALNT2, SNX17, CETP, LIPC) were regarded as dyslipidemia associated genes in the original GWAS study." (PMID 30110382, 2018). "Moreover, LIPC variants might have a pleiotropic effect on one more of the abnormalities associated with metabolic syndrome in humans such as insulin resistance." (PMID 31805754, 2019). "Recent studies have shown pleiotropic associations of LIPC single nucleotide polymorphisms (SNPs), which included lipid profiles, hepatic lipase activity, serum insulin levels, insulin sensitivity, markers for oxidative stress, metabolic syndrome and atherosclerotic cardiovascular diseases." (PMID 30410583, 2018). "In particular, the APOB XbaI (rs693) and the APOE ε4 variants were associated with diverse markers of dyslipidemia and CAD, while an independent role was observed for the LIPC T202T variant." (PMID 38638292, 2024). "Other variants associated with CI2 were observed on KCND3, DIPK2B, and LIPC/ALDH1A2, which have already been identified in lipoprotein and dyslipidemia studies." (PMID 37372394, 2023). "After the subgroup analysis, only rs261332 of the LIPC gene was significantly associated with dyslipidemia in the combined NTE type, but the association was not reproduced in the KCMS population." (PMID 25005712, 2014). "The rs2043085 SNP in the LIPC gene region, where our strongest signal has been observed in fine mapping in the discovery panel, was recently associated with elevated HDL-C in an additional cohort of individuals with mixed dyslipidemia." (PMID 22654671, 2012). "Our findings suggest that simple heterozygotes for LIPC variants have detectable dyslipidemia phenotypes, and that hepatic lipase deficiency may not be a purely recessive condition." (PMID 39518997, 2024). "In a study of Chinese genetic variants in lipid parameters and dyslipidemia, HDL-C levels decreased from 1.38 mmol/L for individuals carrying three or fewer risk alleles to 1.14 mmol/L for individuals carrying all eight risk alleles (MLXIPL rs17145738, LPLrs326, LIPC rs1800588 and CETP rs3764261)." (PMID 28915626, 2017). "Furthermore, LIPC, and rs1532085 in particular, has been associated with the level of HDL-C, total cholesterol and triglyceride, as well as with metabolic syndrome." (PMID 24651390, 2014). "Total hepatic lipase deficiency in humans can increase HDL-cholesterol, while heterozygous carriers of dysfunctional LIPC variants do not have a consistent dyslipidemia phenotype." (PMID 33577783, 2021).
dyslipidemia (continued). "Although some of these studies have focused on genomic regions that are confirmed to harbor dyslipidemia-predisposing loci, such as APOB, CETP, LIPC and LPL, no exhaustive studies testing whether GWAS-discovered loci modify response to treatments have been previously reported." (PMID 22951888, 2012).
Obesity (19 papers, 2009 to 2024). Accumulation of substantial excess body fat. "Dietary fat intake modifies the effect of the variant rs2070895 in LIPC on changes in serum lipids during a long-term weight-loss intervention in adults with obesity." (PMID 39595489, 2024). "Because we had previously determined the interactive effect of sex and obesity on the association of two LIPC promoter SNPs with lipid traits, we performed subgroup and mediation analyses in this extended study of LIPC variants." (PMID 31077211, 2019). "We have previously demonstrated that sex and obesity interacted with two LIPC promoter polymorphisms to determine HDL-C levels in a Taiwanese population." (PMID 31077211, 2019). "The influence of LIPC alleles on obesity was investigated through a reciprocal hemizygosity analysis." (PMID 30410583, 2018). "We performed a case-controlled study (850 obese children and 2119 controls) and evaluated the association between LIPC C-514T polymorphism, obesity and plasma lipid profile in Chinese children and adolescents." (PMID 26282880, 2015). "LIPC was identified as an obesity candidate gene in a mouse model, LIPC deficient mouse can be protected against diet-induced obesity." (PMID 26282880, 2015). "In the present study, we explored the associations between the LIPC C-514T polymorphism, obesity and plasma lipid profiling in a representative sample of Chinese children and adolescents." (PMID 26282880, 2015). "Several studies have explored the relationship of LIPC C-514T polymorphism and obesity." (PMID 26282880, 2015). "We found a significant relationship between the LIPC C-514T polymorphism and obesity in boys." (PMID 26282880, 2015). "LIPC has been reported as a factor involved in the control of energy balance and body fat accumulation, consequently producing an effect on obesity in mice; elevated hepatic lipase activity favours obesity, while its deficiency might protect against obesity 5,23." (PMID 26282880, 2015). "Our findings are in line with those of previous studies, in which associations of multiple LIPC SNPs with HDL-C levels and risks of myocardial infarction and coronary artery disease were influenced by dietary intake, physical activity, sex, and obesity." (PMID 31077211, 2019). "Our data revealed a significant association of three LIPC SNPs with TC, HDL-C, and TG levels, with the interaction of sex and obesity; this finding was consistent with that of our previous study." (PMID 31077211, 2019). "We also compared the plasma lipid levels among LIPC C-514T genotypes stratified by gender and obesity status." (PMID 26282880, 2015). "Hepatic lipase (LIPC) is a key rate-limiting enzyme in lipoprotein catabolism pathways involved in the development of obesity." (PMID 26282880, 2015). "As a key activity determinant, the C-514T genotypic effect was reported to modulate the influence of obesity on LIPC activity." (PMID 26282880, 2015). "In conclusion, the genotype distributions of the LIPC C-514T polymorphism were related to obesity status in a gender-specified fashion, male childhood with T allele might have a higher trend to be obese, while the female childhood with the T allele might tend to be defended against obesity." (PMID 26282880, 2015). "LIPC GA genotype interacted with overweight/obesity to increase SBP and DBP, and AA genotype interacted with overweight/obesity to increase SBP." (PMID 23109900, 2012). "The interactions of LIPC -514C>T and LIPC -250G>A SNPs and obesity on HDL-C levels were also observed in Taiwanese-Chinese men but not in women." (PMID 23039238, 2012). "The overall population is similar to others in this age range in terms of smoking and prevalence of obesity, as well as the distribution of the LIPC genotype." (PMID 21139980, 2010). "The role of LIPC C-514T polymorphism in high density lipoprotein cholesterol (HDL-C) production has been well-established 12,13, but the association of the polymorphism with obesity is less certain." (PMID 26282880, 2015).
Obesity (continued). "The genotypes of ACAT-1 AC, LIPC GA and AA, and SCARB1 TT; LDL-R A-A- and LIPC GA; and SCARB1 TT were interacted with overweight/obesity to increase systolic, diastolic blood pressure (SBP, DBP) and pulse pressure (PP) levels; respectively." (PMID 23109900, 2012). "The SNPs of ABCA-1 (SBP and PP), LDL-R (DBP), LIPC (SBP and DBP), and SCARB1 (PP) were shown interactions with overweight/obesity to influence blood pressure levels (p < 0.01–0.001)." (PMID 23109900, 2012). "In the present study, we showed that the genotypes of ACAT-1 AC, LIPC GA and AA, and SCARB1 TT interacted with overweight/obesity to increase SBP levels, whereas the genotype of ACAT-1 CC interacted with overweight/obesity to decrease SBP levels." (PMID 23109900, 2012). "The interactions of ABCA-1 (SBP and PP), LDL-R (DBP), LIPC (SBP and DBP), and SCARB1 (PP) and overweight/obesity on blood pressure levels were also detected." (PMID 23109900, 2012). "Moreover, proteins responsible for transport of small molecules, namely chylomicron remodeling and assembly of active LPL and LIPC lipase complexes, were not enriched in control vs. obesity comparison." (PMID 38732002, 2024). "The SNPs of ABCA-1 (LDL-C and ApoA1/ApoB); LIPC (TC, LDL-C, ApoA1 and ApoB); LIPG (ApoB); MTHFR (TC, TG and LDL-C); MYLIP (TC and TG); PCSK9 (TG, HDL-C, ApoB and ApoA1/ApoB); PPARD (TG and ApoA1/ApoB); and SCARB1 (TG, ApoA1 and ApoB) interacted with overweight/obesity to modulate serum lipid levels." (PMID 23039238, 2012).
atherosclerosis (16 papers, 2011 to 2025). A disease characterized by the build-up of fatty material and calcium deposition in the arterial wall resulting in partial or complete occlusion of the arterial lumen. "Concordant with those observations, it was formerly reported that in dyslipidemic patients, LIPC polymorphisms would predict response to lipid lowering therapy in terms of atherosclerosis regression." (PMID 23874450, 2013). "Our present observations support a deleterious impact of the LIPC -514T variant on this index of atherosclerosis progression in CAD patients." (PMID 23874450, 2013). "Other research established that atherosclerosis can be induced by LIPC mutation." (PMID 33004870, 2020). "Furthermore, single nucleotide polymorphisms (SNP’s) in the LIPC gene that were associated with elevated LDL-TG levels were simultaneously associated with increased prevalence of atherosclerosis, suggesting the potential role of LDL-TG based on the principles of natural randomization." (PMID 36684605, 2022). "However, data from GWAS-related studies still have not provided concrete evidence for an association between rs1800588 and CAD, and other LIPC SNPs facilitating the generation of oxidative stress signals may contribute to the risk of atherosclerosis and CAD." (PMID 31077211, 2019). "Since previous publications have demonstrated an association between hepatic lipase (encoded by the LIPC gene), LDL-TG and atherosclerosis, we performed a genomic screen of the LIPC gene region." (PMID 36684605, 2022). "Genetic variants in the genomic region encoding hepatic lipase (LIPC) were associated with LIPC gene expression, LDL-TG levels and with atherosclerosis." (PMID 36684605, 2022). "The epistatic effect of CETP and LIPC on HDLc concentrations and atherosclerosis has been previously reported." (PMID 22073289, 2011). "Genetic association between LIPC gene variants, LDL-TG and atherosclerosis." (PMID 36684605, 2022). "The ANXA2-R1 rs17845226 SNP has modest LD (r2 ≥ 0.4) with 34 SNPs, all located downstream of the ANXA2 gene-coding region in the long intergenic region between two genes, FOXB and ANXA2 on chromosome 15, and near the RORA and LIPC loci, which play roles in lipid metabolism and atherosclerosis." (PMID 28456096, 2017). "However, with a clear definition of CAD cases and paired controls taken from the general population, it shows that LIPC T-allele is associated to both the CAD status and to ABI, a marker of atherosclerosis progression." (PMID 23874450, 2013). "CETP and HL are implicated in the metabolism of plasma lipoproteins, but the effects of CETP and LIPC genotypes on atherosclerosis may be dependent on LDL-receptor activity." (PMID 23181436, 2012). "In our data, LIPC gene expression levels were significantly lower and LDL-TG levels were significantly higher in patients with atherosclerosis." (PMID 36684605, 2022). "The hepatic lipase (LIPC) and cholesterol ester transfer protein (CETP) genes are well established genetic factors that influence HDL-C levels and metabolism, as well as atherosclerosis." (PMID 31108953, 2019).
coronary artery disease (11 papers, 2011 to 2025). "A whole-exome sequencing study has revealed that the abnormal combination of the AA genotype of rs17269397 in LIPC and cholesterol levels can affect the risk of coronary artery disease (CAD)." (PMID 37273686, 2023). "Relationship between hepatic lipase (LIPC) polymorphism and coronary artery disease (CAD) has often led to contradictory results." (PMID 23874450, 2013). "Other mechanisms explaining the association of high HDL-C and CVD, include genetic variants, e.g. CETP, ABCA1, LIPC, SCARB1, that lead to extremely high HDL-C concentrations and a higher risk of coronary artery disease and death." (PMID 41239356, 2025). "For instance, certain genetic mutations in LIPC and SCARB1, which have been linked to a higher risk of coronary heart disease." (PMID 39696353, 2024).
hyperlipidemia (11 papers, 2014 to 2025). "Some studies showed a strong connection between the LIPC -250G/A (rs2070895) polymorphism and lipoprotein metabolism disease, such as hyperlipidemia and diabetes." (PMID 30322388, 2018). "In fact, AFB1 suppresses the expression of the aryl hydrocarbon receptor gene, resulting in the elevation of cholesterol observed in this study; hepatic lipase, encoded by the LIPC gene, is also suppressed by AFB1, contributing to hyperlipidemia." (PMID 40421175, 2025). "w., 4 weeks) significantly reduced the levels of TC and triglyceride (TG) in the livers of hyperlipidemia mice, as well as enhanced the activity of total hepatic lipolysis by upregulating the expression of PPARγ and lipid metabolism related genes-lipase member C (LIPC)." (PMID 35847034, 2022).